ACHE (acetylcholinesterase (Yt blood group))
Diseases named in the same sentence as ACHE in open-access papers (continued):
Sharing a sentence is not in itself a finding about the gene and the disease.
prion disease (3 papers, 2015 to 2024). A transmissible disease that is caused by a protein that is able to induce abnormal folding of normal cellular proteins, leading to characteristic spongiform brain changes, which are associated with neuronal loss without an inflammatory response. "In summary, we report that AChE acts as an auxiliary molecule in PrP misfolding, leading to PrP morphotypes with potential relevance in prion diseases." (PMID 25853328, 2015). "Conversely, the cholinergic ChAT mRNA levels were not significantly different, suggesting that prion disease affects AChE in a specific manner." (PMID 25853328, 2015). "Our finding that targeting a druggable site in AChE blocks the formation of these complexes is conceptually attractive and might be used for therapeutic strategies to target prion diseases and other protein misfolding disorders." (PMID 25853328, 2015). "We then examined whether partial AChE gene knockdown in transgenic mice, which reportedly leads to a 25-35% decrease in AChE activity, could affect prion disease tempo in vivo." (PMID 25853328, 2015). "The functional involvement of both AChE and PrP in AD, together with the AChE-PrP assemblies described here, reveals intriguing similarities between AD and prion diseases that could bring fundamental insights into their origins and progression." (PMID 25853328, 2015). "Here we addressed the hypothesis that a broader non-enzymatic function of AChE in PrP misfolding and aggregation could be relevant in prion diseases." (PMID 25853328, 2015). "Conversely, AChE mRNA levels were not changed compared to uninfected mice, indicating that AChE depletion during prion disease occurs via a post-transcriptional process and may be inherently linked to prion replication." (PMID 25853328, 2015).
prostate carcinoma (3 papers, 2015 to 2023). A carcinoma that arises from epithelial cells of the prostate gland. "In prostate cancer patients, Battisti and coworkers observed a decrease in AChE activity in the blood; this opened the possibility of proposing AChE as a cancer biomarker." (PMID 37760598, 2023). "The objective of this study was to investigate the potential effect of the polysaccharides isolated from Hericium novae-zealandiae, a native New Zealand fungus, on the in vitro proliferation of prostate cancer cell lines, gene expression, acetylcholinesterase (AChE) activity, and oxidation." (PMID 31288400, 2019). "On the other hand, Nieto-Cerón and collaborators reported no significant changes in AChE activity between prostate cancer and benign prostatic hyperplasia; however, they analyzed two types of tumors: metastatic and non-metastatic." (PMID 37760598, 2023).
respiratory depression (3 papers, 2023). A decrease in ventilation secondary to impaired signals from the central nervous system. "Acute exposure to OPs can lead to death due to respiratory depression and/or due to SE, both of which are caused by the inhibition of AChE and the excessive elevation of ACh." (PMID 37888716, 2023).
sleep disorder (3 papers, 2020 to 2025). A change from the patient's baseline sleeping pattern, in the hours slept and/or an alteration/dysfunction in the stages of sleep. "Other adverse effects of AChE inhibitors such as extrapyramidal symptoms, sleep disorder and cardiorespiratory adverse effects, are associated with central cholinergic over-activity whereas muscle cramps, weakness and urinary incontinence, are associated with peripheral cholinergic over-activity." (PMID 33321899, 2020).
sudden infant death syndrome (3 papers, 2010 to 2024). Unexpected death in infancy which remains unexplained following autopsy, review of the medical history, and investigation of the death circumstances and death scene. "M2R overexpression and AchE overexpression were also observed in hearts of infants deceased from Sudden Infant Death Syndrome (SIDS)." (PMID 31318899, 2019). "We have recently reported alterations in muscarinic receptor expression and acetylcholinesterase (AchE) activity in tissues from Sudden Infant Death Syndrome (SIDS), a syndrome for which vagal overactivity has been proposed as a potential risk factor." (PMID 21203511, 2010).
tauopathy (3 papers, 2019 to 2021). Neurodegenerative disorders involving deposition of abnormal tau protein isoforms (tau proteins) in neurons and glial cells in the brain. "It has been shown that AChE activity as well as choline acetyltransferase is reduced in the cerebral cortex of patients with AD and tauopathy, indicating degenerated cholinergic neurons in both the diseases." (PMID 34975454, 2021). "The findings of AChE activity in human tauopathy and the mouse model are not consistent." (PMID 34975454, 2021).
acute respiratory distress syndrome (2 papers, 2022 to 2024). Progressive and life-threatening pulmonary distress in the absence of an underlying pulmonary condition, usually following major trauma or surgery. "There is increasing evidence that mechanisms other than AChE inhibition may contribute to the high toxicity of OP, e.g. the formation of lung edema, tissue destruction and alterations in the immune response leading to an acute respiratory distress syndrome." (PMID 34778934, 2022).
Arthritis (2 papers, 2020 to 2023). Inflammation of a joint. "Recently rivastigmine, a known AChE inhibitor, was reported to have therapeutic effects in a complete Freund’s adjuvant-induced model of arthritis." (PMID 32792961, 2020).
Bradycardia (2 papers, 2021 to 2023). A slower than normal heart rate (in adults, slower than 60 beats per minute). "The authors suggested that CAF-induced bradycardia may occur through cholinergic activation by AChE inhibition or ether-a-go-go potassium channel inhibition, impacting cardiac repolarization, and potentially causing bradycardia and cardiac arrest." (PMID 37978123, 2023). "Furthermore, a study also found that copper nanoparticle exposures inhibit AChE activity, which can result in bradycardia although this effect is not specific to cardiac muscles." (PMID 34361024, 2021).
cholangiocarcinoma (2 papers, 2022 to 2023). A carcinoma that arises from the intrahepatic biliary tree (intrahepatic cholangiocarcinoma) or from the junction, or adjacent to the junction, of the right and left hepatic ducts (hilar cholangiocarcinoma). "CAY10603, through its selective inhibition of AChE and subsequent elevation of acetylcholine levels, activates surface receptors on cholangiocarcinoma cells, inducing apoptosis in tumor cells." (PMID 38033576, 2023).
cognition (2 papers, 2015 to 2023). Intellectual or mental process whereby an organism becomes aware of or obtains knowledge. "These compounds are characterized by the ability to reduce the activity of acetylcholinesterase (AChE), which, by decomposing acetylcholine in the synaptic cleft, impedes neurotransmission and thus causes cognition impairment." (PMID 25618762, 2015).
dengue (2 papers, 2009 to 2019). "metabolite inhibits the AchE enzyme in the dengue and filarial vectors." (PMID 30936853, 2019).
heart failure (2 papers, 2021 to 2022). Inability of the heart to pump blood at an adequate rate to meet tissue metabolic requirements. "In humans, 50-60% AChE inhibition produces mild symptoms, 60-90% inhibition produces moderate symptoms, and >90% inhibition causes death due to respiratory or heart failure." (PMID 36267428, 2022).
hippocampal atrophy (2 papers, 2020 to 2025). "Huperzine A (400 μg/day) has demonstrated cognitive benefits as an acetylcholinesterase (AChE) inhibitor in clinical trials, and homotaurine (150 mg twice daily for 78 weeks) was found to slow hippocampal atrophy." (PMID 40077790, 2025). "Donepezil-induced AChE inhibition (six months) in patients who have advanced to mild or moderate AD also slows hippocampal atrophy." (PMID 32414155, 2020).
hyperhomocysteinemia (2 papers, 2008 to 2019). A serious metabolic condition caused by mutations in the MTHFR gene, medications, or nutritional deficiency. "Recently, it has been reported that chronic experimental hyperhomocysteinemia produce cognitive dysfunction, and increase in brain AChE activity." (PMID 18691432, 2008).
Hyperinsulinemia (2 papers, 2021). An increased concentration of insulin in the blood. "Next, our aim was to examine the effect of hyperinsulinemia and exercise on the AChE activity in muscle tissue." (PMID 33708999, 2021). "The present work investigates the molecular mechanisms of high carbohydrate and fat diet in inducing prediabetic hyperinsulinemia and effect of exercise on InsR signaling events, muscular AChE, and lactate dehydrogenase activity." (PMID 33708999, 2021).
hypothyroidism (2 papers, 2015 to 2025). Abnormally low levels of thyroid hormone. "In the present study, it has been demonstrated that there are significant decrements of Ach levels, as well as AChE activity, in the hippocampus of adult-onset hypothyroidism." (PMID 25371181, 2015). "The results demonstrated that hypothyroidism induced a significant decrease of Ach content and AChE activity (by 17 and 34%, respectively), which were restored to control values by T4 administration." (PMID 25371181, 2015). "In conclusion, this study demonstrated that hypothyroidism induces alterations of hippocampal Ach level and AChE activity, as well as syt-1 and SNAP-25 expression, in adult rats." (PMID 25371181, 2015). "Alternatively, the decrease in AChE activity may also result from changes in the turnover of the enzyme proteins in hypothyroidism." (PMID 25371181, 2015). "The effects induced by hypothyroidism on rat hippocampal Ach and AChE remain largely unknown." (PMID 25371181, 2015). "Therefore, in this study, we have investigated the concentration of ACh and the activity of AChE, as well as the expression levels of syt-1 and SNAP-25 in the hippocampus of adult-onset hypothyroidism." (PMID 25371181, 2015).
kidney carcinoma (2 papers, 2016 to 2025). Primary or metastatic malignant neoplasm involving the kidney. "For example, MDM2, SLC16A3, LFT etc. show expression change in renal cancer; SLC22A7, ACHE, BMP4 etc. are associated with renal function." (PMID 27258182, 2016).
kidney damage (2 papers, 2017 to 2021). "In order to study if there was a relationship between kidney damage and pesticide exposure, a correlation study was carried out between kidney damage biomarkers and pesticide exposure (measured by AChE and BuChE)." (PMID 34072924, 2021). "Our results showed that AChE, a biomarker of chronic and low-intensity exposures, correlated with a higher number of biomarkers of kidney damage in the farmers group compared to the NOE group." (PMID 34072924, 2021).
leukemia (2 papers, 2016 to 2018). A malignant (clonal) hematologic disorder, involving hematopoietic stem cells and characterized by the presence of primitive or atypical myeloid or lymphoid cells in the bone marrow and the blood. "In this paper, we describe the isolation, structure determination, plausible biosynthetic pathway, cytotoxicity and inducing apoptosis in leukemia cells, AChE inhibitory activity, and the docking study with AChE of zephycandidine A." (PMID 27658482, 2016). "Thus, it has been reported that donepezil induced caspase activity in leukemia HL-60 cells, whereas other reports described an inhibition of caspases by the AChE inhibitors huperzine A, galantamine, and donepezil, which led to neuroprotective effect in different experimental models." (PMID 30181440, 2018).
mastitis (2 papers, 2025). Inflammation of breast tissue during lactation or postpartum due to an obstructed duct or infection. "We show that blood group genes ABO and ACHE (Cartwright blood group) mediate regulatory effects on protein concentration and mastitis via expression and splicing, supporting conserved and widespread regulatory effects on mammalian complex traits." (PMID 40688095, 2025). "Also, gene expression and splicing of ABO (Histo-blood group) and ACHE (acetylcholinesterase, Cartwright blood group) affected protein concentration and mastitis, respectively." (PMID 40688095, 2025).
melanoma (2 papers, 2020 to 2021). A malignant, usually aggressive tumor composed of atypical, neoplastic melanocytes. "MITFs upregulate AChE expression during melanin production in murine melanoma cells." (PMID 34360837, 2021). "During melanin production in B16F10 murine melanoma cells, AChE levels decrease significantly." (PMID 34360837, 2021).
memory (2 papers, 2020 to 2021). The activities involved in the mental information processing system that receives (registers), modifies, stores, and retrieves informational stimuli. "Scopolamine can produce similar memory deficits seen in the elderly and significantly increase AChE activity and decrease the choline acetyltransferase (ChAT), ACh level and the activities of antioxidant enzymes in the brain of memory-impaired mice." (PMID 32252285, 2020).
myocardial ischemia (2 papers, 2018 to 2024). A disorder of cardiac function caused by insufficient blood flow to the muscle tissue of the heart. "Here, we show that ATF3, a transcription factor that is induced by a variety of stress signals including myocardial ischemia, chemical toxicity of the liver and renal ischemia-reperfusion, down-regulates the expression of AChE, another stress-induced protein." (PMID 29681794, 2018).
nematode infection (2 papers, 2016 to 2022). "Nementin therefore has the potential to reduce the environmental impact of toxic AChE inhibitors that are used to control nematode infections and infestations." (PMID 36002479, 2022). "RNAi results further confirmed that the ace2 gene plays a major role in the interaction of AChE and fosthiazate, although mutation of ace2 did not affect nematode infection." (PMID 27897265, 2016).
ovarian carcinoma (2 papers, 2015 to 2019). A malignant neoplasm originating from the surface ovarian epithelium. "The expression of ACHE and BACH2 proteins was also found to be elevated in ovarian cancer tissue specimens, compared with benign tumors or normal ovaries, and associate with worse patient outcomes." (PMID 30791431, 2019).
pneumonia (2 papers, 2019 to 2022). An acute, acute and chronic, or chronic inflammation focally or diffusely affecting the lung parenchyma, caused by an infection in one or both of the lungs (by bacteria, viruses, fungi, or mycoplasma.). "Although acetylcholinesterase (AChE) inhibition is the predominant toxic mechanism, OP may induce pneumonia and formation of lung edema after poisoning and during clinical treatment as life-threatening complication." (PMID 34778934, 2022). "The relative expressions of both VAChT and AChE mRNA decreased significantly in patients with acute stroke, regardless of concomitant pneumonia (P < 0.01)." (PMID 31615442, 2019).
vitiligo (2 papers, 2013 to 2021). Generalized well circumscribed patches of leukoderma that are generally distributed over symmetric body locations and is due to autoimmune destruction of melanocytes. "In this study, changes in AChE activity were observed in 52 cases of vitiligo patients during repigmentation and depigmentation." (PMID 34360837, 2021). "ACh concentration increased with a significant decrease in the expression of AChE in vitiligo patches that return to normal during pigmentation." (PMID 34360837, 2021). "Acetylcholine (ACh) modulates pigmentation by inhibiting dopa oxidase activity in vitiligo during depigmentation, due to a decrease in melanocyte AChE, while during repigmentation esterase activity increases blocking thls inhibitory effect." (PMID 23807911, 2013). "Mean ACh and H2O2 levels were significantly higher in vitiligo lesions before NB-UVB (p < 0.001), and AChE levels were significantly lower (p < 0.001) compared to both repigmented and control skin." (PMID 34360837, 2021).
Ach (1 paper, 2017). "Acetylcholine (ACh) is a vital neurotransmitter in the brain, the abnormal activity of choline acetyltransferase (ChAT) and acetylcholinesterase (AChE) can cause Ach metabolic disorders, leading to biochemical changes in the central cholinergic nervous system." (PMID 29344413, 2017).
acute liver failure (1 paper, 2017). Rapid deterioration of liver function causing encephalopathy and coagulopathy. "Neostigmine, an AchE inhibitor, has been shown to suppress the elevated expression of proinflammation cytokines in an acute liver failure model." (PMID 28740538, 2017).
alopecia (1 paper, 2022). Hair loss usually from the scalp. "Therefore, the main medicinal herbs may affect alopecia by modulating AChE to regulate ACh signaling in hair follicle stem cells and to regulate the glycerophospholipid metabolic pathway." (PMID 35181715, 2022). "Particularly, AChE and fibroblast growth factor receptor 2 (FGF-2) among the findings overlapped with the target protein derived when alopecia was explored as a disease keyword in the GeneCards database." (PMID 35181715, 2022).
aneurysm (1 paper, 2023). Bulging or ballooning in an area of an artery secondary to arterial wall weakening. "Serum BDNF, TNF-α, caspase-3, AChE, and BChE levels were measured in 20 patients with spontaneous SAH due to aneurysms." (PMID 37873057, 2023).
Apathy (1 paper, 2012). Apathy is a quantitative reduction of interest, motivation and the initiation and persistence of goal-directed behavior, where often the accompanying emotions, thoughts, and social interactions are also diminished. "AChE-I treatment reduces incidence of apathy and improves functioning in patients who present with cholinergic disturbances in limbic and paralimbic cortices, and restoration of function in these brain regions may underlie the behavioral response to AChE-Is." (PMID 22433906, 2012).
asthenozoospermia (1 paper, 2019). "This is supported by a recent report that the 5hmC rate of the sperm ACHE gene is higher in asthenozoospermia and oligoasthenozoospermia men than in normozoospermia men." (PMID 30626059, 2019).
astrocytic tumor (1 paper, 2016). A glial tumor of the brain or spinal cord showing astrocytic differentiation. "AChE is primarily expressed in neurons, and in astrocytes, the expression of AChE is low, except in astrocytic tumors." (PMID 27681882, 2016).
autoimmune disease (1 paper, 2022). A disorder resulting from loss of function or tissue destruction of an organ or multiple organs, arising from humoral or cellular immune responses of the individual to their own tissue constituents. "The polyphenols, sterols, and alkaloids present in Cat’s Claw have shown a positive effect in cholinergic dysfunction, inhibiting AChE activity and DNA repairment, avoiding oxidative stress and inflammation, and thus, cardiovascular and autoimmune diseases." (PMID 35164183, 2022).
Brain atrophy (1 paper, 2023). Partial or complete wasting (loss) of brain tissue that was once present. "Brain atrophy was attenuated and MF treatment reversed the increase in AChE levels." (PMID 37513692, 2023).
brain inflammation (1 paper, 2022). "In conclusion, our results confirm that the zebrafish model of acute DFP poisoning precisely reproduces the key pathological features observed in rodent preclinical models, including AChE inhibition, epileptiform seizures, neuronal death, and microglia-mediated brain inflammation." (PMID 35897817, 2022).
cardiomyopathy (1 paper, 2023). A disease of the heart muscle or myocardium proper. "It has been reported that an AChE inhibitor reduces mitochondrial dysfunction and mitochondrial dynamic imbalance in several heart diseases including cardiac I/R injury, DIC, and high-fat diet-induced cardiomyopathy." (PMID 37691124, 2023).
Central apnea (1 paper, 2023). Apnea resulting from depression of the respiratory centers in the medulla oblongata. "Furthermore, we evaluated the possibility that Pox causes central apnea by exerting effects other than AChE inhibition." (PMID 37990100, 2023).